BAG3 (BAG cochaperone 3)
Diseases named in the same sentence as BAG3 in open-access papers (continued):
Sharing a sentence is not in itself a finding about the gene and the disease.
muscular dystrophy (6 papers, 2017 to 2025). Muscular dystrophy (MD) refers to a group of more than 30 genetic diseases characterized by progressive weakness and degeneration of the skeletal muscles that control movement. "The connection between BAG3 and muscular dystrophies can be found in their association with DCM etiology." (PMID 40869293, 2025). "Defects in BAG3 function have been associated with various muscle and cardiac pathologies, including muscular dystrophy." (PMID 41465490, 2025). "Although the roles of BAG3 in the heart under physiological conditions have not been fully understood yet, BAG3 mutations have been currently associated with DCM and muscular dystrophy in humans, indicating a vital role of BAG3 in cardiac growth and function." (PMID 34679684, 2021). "Bag-3 also appears to be important in humans, with a severe muscular dystrophy linked to loss of Bag-3." (PMID 29271938, 2017). "In humans, defects in BAG3 have been linked to severe childhood muscular dystrophy, and there is evidence that BAG3 may regulate autophagy in certain cell types." (PMID 36142618, 2022).
prostate carcinoma (6 papers, 2014 to 2025). A carcinoma that arises from epithelial cells of the prostate gland. "With the results of an immunohistochemical study of prostate carcinoma, the expression level of BAG3 was observed to progressively increase from low- to well-differentiated carcinoma." (PMID 24895585, 2014). "That study also demonstrated that a low expression level of BAG3 predicted a poor prognosis of patients with prostate carcinoma." (PMID 24895585, 2014). "For example, the stress protein BAG3 can stabilize Mcl-1, resulting in increasing ABT-737 resistance in several cancer types including prostate cancers." (PMID 25811469, 2015).
colon cancer (5 papers, 2018 to 2024). "The underlying molecular mechanisms regulating the sensitivity of colon cancer cells to 5-FU by BAG3, a novel regulator of autophagy, should be further investigated." (PMID 30081850, 2018). "Therefore, this is the first study investigating the role of BAG3 in colon cancer chemoresistance." (PMID 30081850, 2018). "Fisetin, a dietary flavonoid, is known to induce cell apoptosis in HCT-116 colon cancer cells by inhibiting HSF1 from binding to the promoter region of HSP70 and BAG3." (PMID 31878360, 2019). "Since HSP70/BAG complexes protect cancer cells from apoptosis through stabilization of anti-apoptotic Bcl-2 family member proteins, the downregulation of HSP70/BAG3 significantly reduces the levels of BCL-2, BCL-XL, and myeloid cell leukemia 1 (MCL-1) proteins in human HCT-116 colon cancer cells." (PMID 31878360, 2019).
familial dilated cardiomyopathy (5 papers, 2013 to 2025). A a genetic form of heart disease that occurs when heart (cardiac) muscle becomes thin and weakened in at least one chamber of the heart, causing the open area of the chamber to become enlarged (dilated). "In the general population, rare variants in TTN and BAG3 are associated with an increased risk of familial dilated cardiomyopathy, and common variants are associated with a decreased risk of sporadic dilated cardiomyopathy." (PMID 40540274, 2025). "Two mutations in BAG3 were subsequently identified in Japanese patients with familial dilated cardiomyopathy (Arg218Trp and Leu462Pro)." (PMID 25925243, 2015). "A new familial dilated cardiomyopathy (FDCM) was found related to mutations in BAG3 gene." (PMID 30792263, 2019).
hypertrophic cardiomyopathy (5 papers, 2017 to 2024). A condition in which the myocardium is hypertrophied without an obvious cause. "BAG3 is highly expressed in the heart and variants in BAG3 are known to cause myofibrillar myopathy with restrictive or hypertrophic cardiomyopathy." (PMID 28669108, 2017).
myocarditis (5 papers, 2014 to 2025). Myocarditis is a condition that is characterized by inflammation of the heart muscle (myocardium). "A BAG3 mutation carrier with history of acute heart failure (DCM-15 III-2) fulfilled CMR diagnostic criteria for myocarditis with serological evidence of acute Lyme disease and past Parvovirus B19 infection, and a detectable HHV6 genome in the blood." (PMID 25008357, 2014).
neuroblastoma (5 papers, 2013 to 2023). Neuroblastoma (NB) is the most common solid, extracranial childhood tumor. "Among the Hsp70 function complementing proteins, BAG3 overexpresses 4-fold less in the case of neuroblastoma SH-SY5Y and 13-fold more in differentiated SH-SY5Y as compared to extreme stress." (PMID 36979108, 2023). "DNAJB1 overexpresses 7- and 5-fold for neuroblastoma SH-SY5Y [SH] and differentiated SH-SY5Y [SH(D)], respectively; BAG3 at 11- and 6-fold; and HSPH1 at 2.7- and 3.2-fold." (PMID 36979108, 2023). "Our results could explain the link between the expression of ERα and the down-regulation of main players modulating apoptosis (caspase-3, BAG3, BAG1) recently described in human neuroblastoma in absence of ligand." (PMID 23825704, 2013).
restrictive cardiomyopathy (5 papers, 2015 to 2025). A type of heart disorder referring to the inability of the ventricles to fill with blood because the myocardium (heart muscle) stiffens and looses its flexibility. "In the group of patients carrying the other three BAG3 variants, none had lost ambulation and none showed signs of restrictive cardiomyopathy during follow-up." (PMID 40493734, 2025).
small cell lung carcinoma (5 papers, 2014 to 2025). Small cell lung cancer (SCLC) is a highly aggressive malignant neoplasm, accounting for 10-15% of lung cancer cases, characterized byrapid growth, and early metastasis. "On the other hand, glioma multiforme and small cell lung cancer (SCLC) show a high incidence of bag3 gene deletions." (PMID 34741483, 2022). "It was found that BAG3 is also frequently overexpressed in different types of lung cancer, including small cell lung carcinomas (SCLC)." (PMID 32121220, 2020). "The down-regulation of BAG3 in human small-cell lung cancer cell lines was observed to lead to an increased cell death; depletion of BAG3 in an in vivo mouse xenograft model significantly reduced tumor growth and induced apoptosis." (PMID 28680391, 2017). "Lower BAG3 levels in ocular melanomas and small cell lung cancer may indicate distinct cellular origins or regulatory processes." (PMID 41367874, 2025). "We analyzed BAG3 expression in 69 samples (36 small cell lung cancers, 13 squamous cell carcinomas, 13 adenocarcinomas, 4 large cell carcinomas and 3 normal lung samples as control) by immunoistochemistry (IHC), using an anti-BAG3 polyclonal antibody (TOS-2)." (PMID 25149536, 2014).
triple-negative breast carcinoma (5 papers, 2018 to 2025). An invasive breast carcinoma which is negative for expression of estrogen receptor (ER), progesterone receptor (PR), and human epidermal growth factor receptor 2 (HER2). "BAG3 (BCL2-associated athanogene 3) knockdown is known to affect proliferation, migration, and invasion of EGFR-positive triple-negative breast cancer cell lines via AKT and FAK kinases." (PMID 31681584, 2019).
amyotrophic lateral sclerosis (4 papers, 2017 to 2025). Amyotrophic lateral sclerosis (ALS) is a neurodegenerative disease characterized by progressive muscular paralysis reflecting degeneration of motor neurons in the primary motor cortex, corticospinal tracts, brainstem and spinal cord. "HSPB8 functions as a chaperone interacting with the Bcl-2 associated athanogene 3 (BAG3) during autophagy and promotes the removal of misfolded proteins involved in amyotrophic lateral sclerosis (ALS) and other motor neuron diseases, such as TDP-43." (PMID 40385290, 2025). "Alterations in the Hsp70/BAG3/HspB8 complex have been implicated in the accumulation of misfolded proteins and emergence of motor neuron diseases such as amyotrophic lateral sclerosis (ALS) and distal motor neuropathy." (PMID 31209204, 2019).
Arrhythmia (4 papers, 2025). Any cardiac rhythm other than the normal sinus rhythm. "A clear association between BAG3 variants and arrhythmias remains to be established, particularly since previous studies have not identified a strong correlation." (PMID 40278180, 2025).
astrocytomas (4 papers, 2012 to 2025). "The quantification of p62, LC3B, Beclin-1 and BAG3 (autophagosomal molecules) proved that nutrient or oxygen deprivation enhances the autophagy in astrocytoma compared to normal brain tissue." (PMID 33525678, 2021). "We also utilized the human astrocytoma cell line, U-87MG, to evaluate the effect of overexpressed Bag3 on T-Ag levels that are produced upon transfection of U-87MG with a plasmid expressing JCV T-Ag under the control of the CMV promoter." (PMID 22984599, 2012). "We analyzed 350 astrocytomas for autophagy-associated markers LC3B, p62, BAG3, Beclin1 and the lysosomal markers LAMP2 and Cathepsin B (CTSB) to investigate whether also the lysosomal machinery is altered." (PMID 26956048, 2016).
myocardial infarction (4 papers, 2015 to 2024). Gross necrosis of the myocardium, as a result of interruption of the blood supply to the area, as in coronary thrombosis. "Decreased levels of BAG3 protein are also observed in the setting of end-stage HF caused by myocardial infarction." (PMID 39110386, 2024). "More recently, we demonstrated that levels of BAG3 were reduced in mice with diminished cardiac function secondary to a myocardial infarction and that restitution of normal levels of BAG3 using an adeno-associated virus restored near-normal left ventricular function." (PMID 30631036, 2019).
schizophrenia (4 papers, 2016 to 2021). A major psychotic disorder characterized by abnormalities in the perception or expression of reality. "The schizophrenia specific module, SCH_only_M7, was not correlated with any covariates we tested and contained 76 genes with BAG3, DNAJB1,DNAJB4, HSPAH and HSPA6 the top 5 hub genes in this module." (PMID 27898074, 2016).
type 2 diabetes (4 papers, 2015 to 2025). "BAG3 is involved in chaperone-assisted selective autophagy, apoptosis, cell adhesion, and cytoskeleton remodeling, suggesting a protective role for this chaperone against type 2 diabetes." (PMID 37569434, 2023).
Alzheimer disease (3 papers, 2017 to 2023). A progressive, neurodegenerative disease characterized by loss of function and death of nerve cells in several areas of the brain leading to loss of cognitive function such as memory and language. "BAG3 is involved in chaperone-assisted selective autophagy and was already associated to Alzheimer’s disease." (PMID 37004691, 2023).
anaplastic thyroid carcinoma (3 papers, 2017 to 2025). "Protein expression data from BAG3-silenced cells compared to control cells allowed us to identify candidate targets of BAG3-mediated regulation in anaplastic thyroid cancer." (PMID 29487711, 2018). "Evidences from a recent report have demonstrated that BAG3 protein sustains anaplastic thyroid carcinoma (ATC) growth either in vitro or in vivo." (PMID 29113311, 2017). "BAG3 protein is an apoptosis inhibitor and is highly expressed in Anaplastic Thyroid Cancer." (PMID 29487711, 2018).
chronic lymphocytic leukemia (3 papers, 2009 to 2024). "This study investigates the role of BAG3 within stromal fibroblasts and its interaction with B-cell chronic lymphocytic leukemia (B-CLL) cells." (PMID 39198407, 2024). "This same increased apoptosis was reported when BAG3 was silenced in acute and chronic lymphocytic leukemia cells." (PMID 19352495, 2009).
distal myopathy (3 papers, 2018 to 2025). Distal myopathy refers to a group of muscle diseases which share the clinical pattern of predominant weakness and atrophy beginning in the feet and/or hands. "Altogether, our results lead us to conclude that the accumulation of mutant Hspb8K141N combined with an inability to degrade Hspb8-positive aggregates through Hspb8/Bag3-mediated autophagy is a key pathomechanism underlying the peripheral neuropathy and distal myopathy in our mouse model." (PMID 28780615, 2018). "Accordingly, mutation or deficiency in p62, BAG3, and HSPB8 has been shown to induce distal myopathy associated with rimmed vacuole and myofibrillar disorganisation on muscle biopsy." (PMID 28780615, 2018).
familial cardiomyopathy (3 papers, 2014 to 2019). An instance of cardiomyopathy that is caused by an inherited modification of the individual's genome. "BAG3 regulates myocyte contraction through interaction with L-type calcium channels, thus BAG3 mutations have been associated with different forms of familial cardiomyopathy, including DCM." (PMID 30792263, 2019). "Besides, closer inspection of rat cluster 1 reveal genes known to have disease mutations in hereditary cardiomyopathy in humans (Bag3, Cryab, Kras, Emd, Plec)." (PMID 24391511, 2014). "All candidate genes but one (SLC39A8) exhibit preferential expression in striated muscle tissues and mutations in TTN, BAG3, FLNC and FHOD3 are known to cause familial cardiomyopathy." (PMID 28296976, 2017).
head and neck cancer (3 papers, 2022 to 2025). A primary or metastatic malignant neoplasm affecting the head and neck. "By analyzing BAG3 expression across various head and neck cancer types and correlating it with disease-free survival, the study aims to elucidate BAG3 positivity’s influence on cancer progression." (PMID 40507324, 2025). "Currently, there is limited specific information available on how BAG3 overexpression affects distinct subtypes of head and neck cancers." (PMID 40507324, 2025). "In this study, the expression of BAG3 has been investigated by immunohistochemistry in a series of head and neck cancers from different anatomical regions." (PMID 40507324, 2025). "This study examines the role of BAG3, a protein involved in cell survival and stress response, as a potential prognostic marker in head and neck cancers." (PMID 40507324, 2025). "Head and neck cancer showed particularly high bag3 mRNA levels, then likely confirming this characteristic as a signature of fibrotic solid tumors." (PMID 34741483, 2022).
Hypertension (3 papers, 2023 to 2025). The presence of chronic increased pressure in the systemic arterial system. "For PC1, shared genetic variants with diastolic blood pressure (ATXN2, GOSR2, NOS3, BAG3) and hypertension (ATXN2, VEGFB, NOS3, BAG3) were also observed." (PMID 39543113, 2024).
ischemia (3 papers, 2022 to 2025). A hypoperfusion of the BLOOD through an organ or tissue caused by a PATHOLOGIC CONSTRICTION or obstruction of its BLOOD VESSELS, or an absence of BLOOD CIRCULATION. "Exposure of BAG3-depleted HSMCs to 6 h of simulated ischemia was associated with decreased LC3-II/-I ratio, suggesting decreased autophagy (LC3-II/-I ratio in shControl vs. shBAG3, 0.45 ± 0.03 vs. 0.30 ± 0.01, * p < 0.05)." (PMID 36142618, 2022). "Our in vitro data showed increased necroptosis marker expression in human skeletal muscle cells exposed to simulated ischemia with BAG3 knocked down." (PMID 36142618, 2022). "In our in vitro experiments, BAG3 was induced in human skeletal muscle cells by simulated ischemia in a time-dependent manner, whereas depletion of BAG3 by shRNA resulted in a decreased number of live cells, suggesting a pro-survival role of BAG3." (PMID 36142618, 2022). "To better understand the role of reduced BAG3 expression on the severity of skeletal muscle injury in ischemia, we knocked down BAG3 in HSMCs and exposed the cells to ischemia, followed by an assessment of cell viability." (PMID 36142618, 2022).
lung adenocarcinoma (3 papers, 2024 to 2025). A carcinoma that arises from the lung and is characterized by the presence of malignant glandular epithelial cells. "For example, in lung adenocarcinoma, FAM111B modulates the expression of BCL2 and BAG3 to facilitate cell proliferation, and FAM111B exhibits peak expression levels during the early G0 phase and late S phase of the cell cycle." (PMID 40781291, 2025).
medulloblastoma (3 papers, 2012 to 2025). A malignant, invasive embryonal neoplasm arising from the cerebellum. "In medulloblastoma tissue, BAG3 expression also correlates with tumor grade and shorter patient survival." (PMID 32121220, 2020). "Using Daoy human medulloblastoma cells, they performed a lentiviral depletion of BAG3 and observed reduced migration and invasion, as well as a cell cycle arrest at the S phase." (PMID 32121220, 2020). "Here, we investigated the possible impact of Bag3 on T-Ag expression in JCV-infected human primary glial cells as well as in cells derived from T-Ag-induced medulloblastoma in transgenic animals." (PMID 22984599, 2012).
metastatic melanoma (3 papers, 2017 to 2022). A melanoma that has spread from its primary site to another anatomic site. "High BAG3 expression has previously been associated with a worse prognosis and poorer survival in aggressive cancers such as pancreatic adenocarcinoma medullablastoma and metastatic melanoma." (PMID 29644001, 2018). "Results shown in this report describe that BAG3 is highly expressed in in the majority of metastatic melanoma carrying the BRAFV600E mutation and, therefore, this protein could be a possible therapy target." (PMID 29113311, 2017).
pancreatic adenocarcinoma (3 papers, 2015 to 2025). "BAG3 has been shown to be overexpressed in tumour cell lines and solid tumours including small cell lung carcinomas, glioblastomas and pancreatic adenocarcinomas where it’s overexpression is associated with poor survival." (PMID 29644001, 2018). "Therapeutically, targeting extracellular BAG3 with monoclonal neutralizing antibodies in murine pancreatic adenocarcinoma models reduced fibrosis and macrophage infiltration, resulting in inhibited tumor progression." (PMID 41367874, 2025). "Furthermore, BAG3 is detectable in the blood of patients affected by pancreatic adenocarcinoma." (PMID 41367874, 2025).
scoliosis (3 papers, 2020 to 2022). A congenital or acquired spinal deformity characterized by lateral curvature of the spine. "It is worth mentioning that the BAG3 c.772C>T variant was also found as the only possible pathogenic variant in another patient from our department, who has proximal limb weakness, scoliosis, and scapular winging." (PMID 33041974, 2020).